TTK (TTK protein kinase)
Diseases named in the same sentence as TTK in open-access papers (continued):
Sharing a sentence is not in itself a finding about the gene and the disease.
tumor (continued). "TTK, MCM2, CLDN7 and TSPAN13 promote tumor cell proliferation and their overexpression could stimulate drug resistance." (PMID 26515599, 2015). "Strong expressions of URLC10, TTK, KOC1 and MHC class I antigens were observed in the tumor cells." (PMID 24708624, 2014). "Using a combined geneset of these 5 remaining cell cycle-related genes (BUB1B, CCNB1, CCNB2, TTK and CDK1) as well as ADAM7 and FAM72B, we also observed a statistically-significant reduction in disease-free survival of patients with tumours exhibiting alterations in gene expression (p = 0.015)." (PMID 25519703, 2014). "To analyze the behavior of tumor and therapeutic cells, we labeled the former with a CMV promoter regulated Pluc-eGFP chimerical reporter, and the latter with a different trifunctional chimerical reporter comprising Rluc-RFP and tTK activities." (PMID 22529983, 2012). "Similarly, in vivo xenograft tumors with TTK knockdown grew more slowly than their counterparts without TTK knockdown, further supporting the role of TTK in tumor progression." (PMID 40269198, 2025). "To further test the tumor-promoting role of TTK, we conducted a series of experiments to test whether inhibiting TTK activity with its specific inhibitor AZ3146 might replicate the effects of TTK downregulation." (PMID 36829176, 2023). "In contrast, TTK increased cell migration and epithelial-to-mesenchymal transition (EMT) by enhancing the expression of dihydropyrimidinase-like 3 (DPYSL3) followed by the increase of snail-regulated EMT, thus reinforce metastatic potential and ultimately tumor metastasis." (PMID 32121246, 2020). "The expression of TTK in tumor regions is higher than that in non-tumor regions." (PMID 32121246, 2020). "In previous work we observed that cytotoxic tTK expressing hAMSCs that targeted the GSC niche differentiated to vascular components in close proximity to CD133 expressing GBM cells and were capable of reducing tumor burden by a factor or 104 in the presence of GCV." (PMID 31267022, 2019). "However, the TTK upregulation was not statistically correlated with the gender, age, and tumor size (P>0.05)." (PMID 24905462, 2014). "TTK is of particular interest since others have reported that reducing levels of TTK sensitized human tumor cells to sub-lethal doses of taxol, whereas nontumorigenic cells could not be sensitized to taxol." (PMID 22509301, 2012). "Most of the significantly up-regulated genes were involved in cell cycle/mitosis/cell division (e.g., TTK, CENPF, NEK2), while many of those down-regulated were involved in cell adhesion/cell cycle arrest (e.g., ADRB2, APLP2, MACF1), consistent with a role of these genes in neoplasia development." (PMID 18297132, 2008). "Overall, we identified CENPF, BUB1, BUB1B, KIF23 and TTK as potentially key genes involved in regulating hypoxia-induced tumor cell stemness, and found that AC079160.1-miR-539-5p-CENPF axis may be involved in regulating hypoxia induced tumor cell stemness in LUAD." (PMID 33148251, 2020). "Conversely, depleting TTK expression in MDA-MB-231 cells not only inhibited their organoid growth in 3D-cultures, but also sensitized them to the tumor suppressing activities of c-Abl independent of its subcellular localization." (PMID 28661474, 2017). "However in this study, we report that, contrary to expectation, stable aneuploid cell lines are more sensitive to TTK inhibition than CIN lines, irrespective of the tumor tissue origin of the cell lines." (PMID 28415765, 2017).
TTK also shares sentences with these, for which no sentence is quoted: non-small cell lung carcinoma (8 papers); clear cell renal cell carcinoma (4); Fanconi anemia (3); squamous cell carcinoma (2); anemia (1); Anxiety (1); bronchiectasis (1); cervical squamous cell carcinoma (1); diabetes (1); diffuse large B-cell lymphoma (1); endometrial tumors (1); endothelial dysfunction (1); fungal infections (1); head and neck squamous cell carcinoma (1); hepatitis C (1); Hodgkins lymphoma (1); infection (1); influenza (1); injury (1); large cell lung cancer (1); leiomyosarcoma (1); leukemia (1); liposarcoma (1); lymphoma (1); mantle cell lymphoma (1); metastasis (1); periodontitis (1); prion disease (1); pulmonary disease (1); Renal Cell Cancer (1).
A further 6 diseases each share a sentence with TTK in 1 paper.